ISG15 (ISG15 ubiquitin like modifier)
Diseases named in the same sentence as ISG15 in open-access papers (continued):
Sharing a sentence is not in itself a finding about the gene and the disease.
infection (continued). "In addition, downregulated phosphorylation of STAT1 and STAT2 were observed in ISG15-/- mice after infection with PRV in vivo." (PMID 36146669, 2022). "Notably, multiple antiviral proteins were also dramatically decreased in PAMs during the PRRSV-ADE infection, including ISG15, ISG20, IFIT1 (ISG56), IFIT2 (ISG54), IFIT3 (ISG60), IFIT5 (ISG58), OAS1, Mx1, RSAD2, TRIM22, TRIM25 and TRIM34, except for TRIM52." (PMID 36680075, 2022). "ISG-15 protein expression at 24 h post-infection also showed the same pattern (p = 0.0038)." (PMID 36146585, 2022). "Interestingly, ISG15 has been reported to be both advantageous and detrimental to the development of immunopathology during infection." (PMID 36416643, 2022). "As anticipated, ISG15 complementation of control cells, which endogenously express ISG15, did not change susceptibility to infection with or without IFN-I-priming." (PMID 35333911, 2022). "Furthermore, all identified infection-associated ISG genes (MX1, MX2, OAS1Y/Z, OAS2, ISG15, IFI6, IFI44 and RSAD2) showed lower expression values in Holstein infected cells relative to Sahiwal." (PMID 35061738, 2022). "Interestingly, ONNV at the different tested MOIs strongly increased the expression of the antiviral innate immune genes RIG-I, MDA5, IFN-β, and ISG15 with a significant and more robust effect at 24 h post infection." (PMID 36611893, 2022). "IFN-related genes with significant low expression in later infection, such as ISG15 and IFI6, might be involved in creating a permissive environment for late-stage parasite development and replication." (PMID 35443155, 2022). "Interestingly, ISG15, an interferon-stimulated gene involved in ubiquitination of newly synthesized genes, was weakly expressed in the highest-dose infection and more strongly expressed in the lower doses." (PMID 35993785, 2022). "Additionally, PLpro can cleave both ubiquitin and the ubiquitin-like protein ISG15 from host cell substrates as a mechanism to evade innate immune responses during infection." (PMID 36548304, 2022). "All virus increased ISG15 mRNA levels 12 h after infection, however, ISG15 induction was terminated earlier for UV-PRV than PRV, and not notably terminated for gE-deleted PRV, which continued to produce high levels of ISG15 transcripts even at a late stage of infection (36 h)." (PMID 36315588, 2022). "Importantly, infection of PAMs by PRRSV vaccine strains promoted the secretion of extracellular ISG15 from infected PAMs." (PMID 35498732, 2022). "During E30 infection, genes associated with the type I IFN signaling pathway (Isg15, Mx1, Mx2, Sp100, Ifit1, Ifit3, Ifih1, Irf7, Irf9, guanylate-binding proteins 2 [Gbp2], and Stat1) and defense response to viruses (Ddx58, Ddx60, Zbp1, Oas2, Nlrc5, and Eif2ak2) were significantly upregulated." (PMID 36147849, 2022). "In addition, ISG15 itself in its unconjugated form can be secreted both by myeloid cells and lymphocytes to potentially recruit and activate immune cells to sites of infection." (PMID 36416643, 2022). "However, at 12 h and 3 days post-infection in rVHSV-P-infected cells and fish, respectively, the expression of ISG15 and Mx was similar to that in rVHSV-wild-infected cells and fish." (PMID 33465148, 2021). "In essence, the ISG15 knockout may have resulted in unknown changes to the typical protein ISGylation profile with subsequent unpredictable alterations in infection modulation." (PMID 34299120, 2021). "However, what was striking was the lower abundancy of proteins involved in response to infection (ISG15, NME2, IFNγ, and C3)." (PMID 34962717, 2021). "Furthermore, a dampened induction of several downstream ISGs, including MX1, OAS1, ISG-15, and viperin was observed on day 4 post-infection." (PMID 33653328, 2021). "We also measured Tnfa, Il1b, Il6 and Isg15 expression and found that macrophages infected with plasmid-cured R. equi (33701-) had reduced expression of Tnfa at 8h, and of Il6 at both 4- and 8h after infection." (PMID 34473814, 2021).
infection (continued). "Because ISG15 acts as chemoattractant for neutrophils, their increased infiltration at the site of infection might be fueled by the extensive PB response." (PMID 34723157, 2021). "At 12 and 24 hpi, single‐molecule RNA FISH was performed using probes specific for the SARS‐CoV‐2 genome and for ISG15 which was found to be highly upregulated upon infection and has the highest ‐log10 P‐value in the differential analysis comparing bystander cells vs mock‐infected cells." (PMID 33904651, 2021). "For example, ISG15 is an interferon-stimulated, ubiquitin-like protein which regulates mitochondrial homeostasis and targets various proteins involved in catabolic autophagy metabolism in the mitochondria (mitophagy) during infection." (PMID 33980308, 2021). "The overexpression of circDtx1 could significantly inhibit the expression levels of interferon IFN1, inflammatory cytokines (TNF-α), and antiviral genes such as myxovirus resistance protein 1 (MX1) and ISG15 after SCRV infection." (PMID 33735323, 2021). "Although the precise role of ISG15 remains to be determined, its' up-regulation during pregnancy may protect the conceptus against infection and promote placental development and vascularization." (PMID 33898551, 2021). "ISG15 knockout was previously found to enhance T. gondii growth in A549 cells and this was attributed to its role in the targeting of autophagy machinery to the PV during infection leading to restriction of parasite growth." (PMID 34871166, 2021). "Moreover, the results showed that IFN1, TNF-α, MX1, and ISG15 were significantly decreased by the introduction of miR-15a-5p mimics upon SCRV infection." (PMID 33735323, 2021). "The expression of IFN-β and ISG15 were detected at the indicated time points after infection." (PMID 34630361, 2021). "However, concomitant with the higher gene expression observed, Mx1 and ISG15 reach higher protein levels in A549/PKR KO cells than in A549/Scr control cells at late times after infection." (PMID 34372519, 2021). "Nevertheless, because of the reduced protein synthesis in IFN-α–treated ISG15-deficient cells, cells later become nonpermissive to infection, even when key ISGs are eliminated." (PMID 32423918, 2020). "In MBrC cells, knockdown of MARL could also significantly inhibit the expression of IFN-2, TNF-α, Mx1, and ISG15 upon SCRV infection." (PMID 32678830, 2020). "Notably, ELISA results demonstrated that infection with the PRRSV vaccine strain induced secretion of ISG15 that extracellularly appeared to function as a cytokine that induced PAMs to assume an anti-viral state which resists PRRSV infection." (PMID 32927637, 2020). "Other UbLs play important roles in different types of stress responses as illustrated by involvement of URM1 and UFM1 in the regulation of oxidative stress and ER stress, respectively, and by the involvement of FAT-10 and ISG15 in the cellular and immune response to infection." (PMID 32752270, 2020). "Interestingly, reduced deISGylation and DUB function did not disrupt Lpro’s ability to block IFN and ISG expression during infection, although overexpression of ISG15 resulted in a significant reduction of FMDV replication." (PMID 32295921, 2020). "Previous studies demonstrated that robust ISG15 expression in the endometrium may facilitate conceptus attachment or improve the resistance against infection." (PMID 32708974, 2020). "Embryo mortality increases in ISG15-/- mice, and ISG15 may affect fetal growth, placenta development, and potential infection defense mechanisms in humans." (PMID 32138165, 2020). "Infection of A549 cells with 1 MOI of RSV-A2 induced Heatr9 expression with a significant positive correlation when plotted against interferon stimulated gene 15 (Isg15) induction." (PMID 32678841, 2020). "It should be noted that conjugation-independent functions of ISG15 may also contribute to the control of infection." (PMID 32752270, 2020).
infection (continued). "Taken together, these results suggest that both low-virulence PRRSV strains (both VR2332 and TJM) could induce expression of intracellular ISG15, while infection of PAMs with PRRSV vaccine strain TJM could additionally induce secretion of extracellular ISG15." (PMID 32927637, 2020). "Nevertheless, virus resistance results from a lack of IFN signaling control—as a consequence of ISG15 loss of function—which would explain why ISG15-deficient patients were not more susceptible to severe infection." (PMID 32423918, 2020). "In miiuy croaker brain cells (MBrC), MAVS-specific siRNA could also significantly suppress the expression of IFN-2, TNF-α, Mx1, and ISG15 upon SCRV infection." (PMID 32678830, 2020). "Genes encoding antimicrobial innate immunity peptides (including the defensin class of peptides) and immunity-related genes (e.g., ISG15) were also upregulated during puberty, supporting a role for Sertoli cells in protecting the testis from infection, especially after sexual maturation." (PMID 31928944, 2020). "Similarly, Irf7, Isg15 and Stat2 mRNA levels were decreased in axillary lymph nodes of xeno mice 7 days post-infection relative to control mice." (PMID 33031404, 2020). "In agreement with the in vivo results, the production levels of Ifnb, Isg15, and Ccl5 were much higher in the carvedilol-treated WT peritoneal macrophages, whereas the virus titers were lower after the infection." (PMID 33243993, 2020). "Such pathways may be blocked by PRRSV-VR2332 infection which could be a possible explanation for the inconsistencies of intracellular and extracellular ISG15 levels in VR2332-infected PAMs." (PMID 32927637, 2020). "In addition, many metabolic enzymes such as glucose-6-phosphate isomerase and phosphoglycerate kinase 1 are also modified by ISG15 following infection with Listeria either at dimerization domains or at active sites of the enzyme." (PMID 31772204, 2019). "In addition, we have observed that ISG15 modification occurs at known acetylation sites following infection, and on extracellular/secreted and mitochondrial proteins." (PMID 31772204, 2019). "As such, knockdown of ISG15 increases HCMV productive infection in cultured cells." (PMID 31798565, 2019). "Interestingly, we also found evidence for modification of Ubiquitin on K6 and K29 and modification of ISG15 on K35 in wild-type infection conditions and on K8 in USP18C61A/C61A KI mice." (PMID 31772204, 2019). "In addition to IFN secretion, we also evaluated the expression of ISG15 protein by Western blot in HIE following VA1 infection." (PMID 31671153, 2019). "Furthermore, our strategy allowed us to determine the strict ubiquitylome in liver tissue from Isg15−/− animals prior to and following infection with Listeria monocytogenes in order to identify the ISGylome." (PMID 31772204, 2019). "It is also possible that HCMV manipulates levels of ISG15 to shift monocytes toward the mixed M1/M2 macrophage phenotype that is observed during infection and hypothesized to enhance viral dissemination and persistence." (PMID 31921100, 2019). "In addition, ISG15 can be upregulated in an interferon-independent manner following infection with bacterial pathogens, such as Listeria monocytogenes and Mycobacterium tuberculosis." (PMID 31772204, 2019). "In addition, ISG15 functions through three distinct modes of action, which likely play complementary roles in various tissues following infection." (PMID 31772204, 2019). "While our primary goal was to identify ISG15 sites, determining the strict ubiquitylome in Isg15−/−animals allowed us to gain insight into how ISG15 and ubiquitin modifications cooperate during an infection." (PMID 31772204, 2019). "Free ISG15 may therefore be a novel modulator of the immune response to an infection, and it remains to be investigated if other IL-1β activating infections can be influenced by ISG15." (PMID 29891555, 2018).
infection (continued). "However, at the site of infection within the peritoneal exudate, we observed an increased number and frequency of DCs in ISG15-treated infected mice." (PMID 29891555, 2018). "Interestingly, IRF3 and IRF7 were only upregulated in head kidney samples after infection with the high virulent reassortant; however, ISG15 and Mx were upregulated in both tissues analyzed." (PMID 30065724, 2018). "It will be interesting to determine whether this observation is restricted to the infection with Toxoplasma or whether this is a general feature of free ISG15 function." (PMID 29891555, 2018). "Thus, we concluded that the presence of CD8α+ DCs is essential for ISG15 to be able to boost IL-1β levels during infection." (PMID 29891555, 2018). "However, transcription levels of IFN-β, IFN-λ, ISG56, CCL5, and IL-6, and expression levels of STAT1, pSTAT1, and ISG15 were similar in A549 cells after infection with all 4 recombinant viruses." (PMID 30050872, 2018). "As ISG15 has a preference for newly synthesised proteins, this may be a way of eliminating viral proteins which are produced in vast excess following infection, as they could potentially be cleared by ISGylation, aggregation and autophagy." (PMID 28186990, 2017). "Similar to IFI35 and ISG15, it showed a consistent infection-induced transcriptional response." (PMID 28993767, 2017). "In addition, measurement of the IFN stimulated genes (ISGs) IP10 and ISG15 support a stronger antiviral response during infection with the MS3 virus." (PMID 28264033, 2017). "Indeed, we observed that IFITM3 and ISG15 protein levels were greatly elevated in spleen, mesenteric lymph node, inguinal lymph node, and sub-maxillary node in pigs after the infection." (PMID 29312239, 2017). "All viruses increased ISG15 mRNA levels 12 h after infection; however, ISG15 induction was terminated earlier for HCMV than UV-HCMV, and not appreciably terminated for CR208, which continued to produce high levels of ISG15 transcripts even at a late stage of infection (72 h)." (PMID 27564865, 2016). "To test this hypothesis, we first compared the effects of wild-type HCMV, UV-HCMV, and IE1-deleted mutant virus (CR208) infection (MOI of 3) on ISG15 transcription by RT-PCR." (PMID 27564865, 2016). "ISG15 expression was increased in cells with the increase of MOI (multiplicity of infection)." (PMID 27659523, 2016). "To determine which signaling pathway was responsible for the Listeria-induced ISG15 transcript and to help identify the cellular compartment in which bacteria are sensed, we made use of Listeria strains that are impaired at different stages of infection." (PMID 26259872, 2015). "Enhancement of the IFN-Stimulated Gene transcription such as ISG15 and Viperin, was also observed in Optn-deficient cells at 9h post-infection, compared to control or Optn-reconstituted cells, without affecting the NF-κB-dependent transcription of IκBα gene." (PMID 25923723, 2015). "ISG15 protein levels increased relatively rapidly; the unconjugated protein was already present at 6 hr post infection and accumulated steadily throughout the infection." (PMID 26259872, 2015). "In order to assess whether UBE2L6 and TRIM25 are induced as rapidly as ISG15 at the protein level, we monitored their expression by immunoblot at 3 hr post infection." (PMID 26259872, 2015). "To assess whether MAGT1 was ISGylated following infection, we immunoprecipitated ISG15 and could show that there is a higher molecular weight MAGT1 complex that immunoprecipitates with ISG15." (PMID 26259872, 2015). "Recent studies have shown that ISG15 is conjugated to newly synthesized proteins, a potential cellular strategy to disrupt the function of viral proteins, which are abundantly produced during infection." (PMID 24854014, 2014).
infection (continued). "Further investigations on how these different processes are regulated by ISG15 and how these events affect downstream immune functions in vivo will be required to understand the role of ISG15 in the generation of tissue protective responses during infection with different pathogens." (PMID 24137104, 2013). "A recent report indicated that HerC5 mainly conjugates ISG15 to newly synthesized proteins in tissue culture and may by that mechanism largely target de novo synthesized viral proteins during infection." (PMID 22272257, 2012). "Infection with RNA viruses or transient transfection with dsRNA can directly and rapidly induce early ISGs, such as ISG15, through IRF3, after activation of the RIG-I/MAVS pathway and recruitment of TRAF3, an essential adapter which recruits the downstream IRF3 kinases TBK1/IKKε." (PMID 22022264, 2011). "Similar to IFNβ mRNA induction, IRF7, Mx1 and ISG15 mRNA levels could also be detected as early as 3 hrs post-infection, with peak levels observed at 16 hrs post-infection." (PMID 22028657, 2011). "However, its activity appears to be negatively controlled by ISG15 and the ISGylation process, either after cotransfection with the ISG15 and the ISG15-conjugating enzymes or as shown here, in a model of infection with HCV." (PMID 22022264, 2011). "Therefore, we conclude that ISG15 contributes to the control of CHIKV during neonatal infection, but redundant mechanisms are responsible for the control of CHIKV during adult infection." (PMID 22028657, 2011). "ISG15 was one of the genes highly activated during infection with both viruses." (PMID 19798428, 2009). "However, after VVΔE3L infection the ISG15−/− mice displayed signs of disease within 2 days, characterized by ruffled fur and lack of activity, and 25% of the animals died within 1 to 2 days." (PMID 18604270, 2008). "In mice lacking ISG15, infection with VVΔE3L caused significant disease and mortality, an effect not observed in VVΔE3L-infected ISG15+/+ mice." (PMID 18604270, 2008). "The finding in this study that G protein expression inhibits IFNβ and ISG15 protein expression is consistent with evidence suggesting that IFNβ and ISG15 are induced in parallel as a primary response to infection, and that this pathway is targeted by RSV G protein." (PMID 18851747, 2008). "Cluster 1 was more heterogenous and lacked a distinct transcriptional profile, whereas Type I IFN (Isg15, Ifi206, Ifit3, Ccl5) and proliferative signatures (Cdk1, Mki67, Tuba1b) were observed in clusters 3 and 5, respectively, whose numbers remained stable between days 7 and 14 after infection." (PMID 39989461, 2025). "Similarly, the induction of ISG15 by HMPV was more induced in adult cells on day 5 after infection." (PMID 40143308, 2025). "Thus, our results reveal important mechanistic insights into USP18-mediated ISG15 hydrolysis and could inform the development of deISGylase inhibitors relevant to infection and other interferon-related diseases." (PMID 40436319, 2025). "In addition to ISG15 itself, the expression of this core conjugation machinery is also triggered by interferon, which explains the massive increase in protein ISGylation following infection." (PMID 40631552, 2025). "Indeed, infection of parental A549 cells with PR8-NS1(N80) mutant virus resulted in lower accumulation of PA protein and higher induction of IFN-stimulated genes IFIT1 and ISG15 compared to infection with the WT virus at the same multiplicity of infection (MOI)." (PMID 38629840, 2024). "The infection status of AM-Cd36 was further supported by the transcriptional alterations observed between virus-positive and virus-negative cells in AM-Cd36, of which genes related to “response to virus” (such as Mx1 and Isg15) and “apoptosis” (such as Bax and Foxo3) were upregulated." (PMID 39414783, 2024).